NLRP3 (NLR family pyrin domain containing 3)
Diseases named in the same sentence as NLRP3 in open-access papers (continued):
Sharing a sentence is not in itself a finding about the gene and the disease.
ischemic stroke (continued). "Melatonin also mitigated NOD-like receptor family pyrin domain-containing protein 3 (NLRP3) inflammasome activation and nuclear factor (NF)-κB/gasdermin D-mediated pyroptosis in microglia following ischemic stroke, while exhibiting the capacity to attenuate the immune response to ischemia in mice." (PMID 40536992, 2025). "Additionally, in an in vitro OGD/R model simulating ischemic stroke, circFndc3b overexpression significantly mitigated NLRP3 inflammasome‐mediated microglial pyroptosis after OGD/R, while its knockdown exacerbated these effects." (PMID 39467260, 2025). "Therefore, the purpose of this study was to investigate the effects of subclinical doses of esketamine on serum NLRP3 levels in elderly patients with ischemic stroke after general anesthesia neurointerventional procedures." (PMID 40417311, 2025). "Studies have shown that TEAS, by adjusting the SIRT1/FOXO3a and SIRT1/BRCC3/NLRP3 signaling pathways following ischemic stroke, inhibits cell apoptosis, oxidative stress, and inflammation of the nerve to reduce brain damage and accelerates the recovery of neurons and some functional metabolism." (PMID 39665041, 2024). "The NLRP3 inflammasome, a significant mediator, could generate pro-inflammatory factors that orchestrate the inflammatory response and tissue damage in ischemic stroke." (PMID 38743119, 2024). "One study investigated the role of trimethylamine N‐oxide in ischemic stroke and found it could promote the activation of the NLRP3 inflammasome in microglia through the FTO/IGF2BP2 pathway, thereby aggravating neurological injury in ischemic stroke." (PMID 39161158, 2024). "We found that ischemic stroke initiates a cascade of complex intracellular processes beginning with oxidative stress that activates the nuclear factor kappa-light-chain-enhancer of activated B cells (NF-κB) consequentially activating the NLRP3 inflammasome." (PMID 41542272, 2024). "BHB exerts an inhibitory influence on NLRP3 inflammasome activation through multifaceted pathways, as depicted in the following illustration, thereby offering a potential therapeutic strategy for mitigating neuronal injury induced by ischemic stroke." (PMID 39075604, 2024). "A number of studies have shown that NLRP3 could be triggered by ischemic stroke and aggravate brain injury." (PMID 38178174, 2024). "The NLRP3 inflammasome initiates inflammatory responses that exacerbate ischemic stroke." (PMID 41542272, 2024). "Thus, our results elucidated that ChemR23 signaling regulates NLRP3-inflammasome activation in ischemic stroke." (PMID 38178174, 2024). "Previously, our group found that NLRP3 could aggravate the recurrent ischemic strokes following a single infarction in an inflammasome-dependent manner." (PMID 38216560, 2024). "The NLRP3 inflammasome is a major mediator of inflammatory responses during ischemic stroke." (PMID 39075604, 2024). "In a mouse model of ischemic stroke, minocycline treatment (1–50 mg/kg/day of minocycline for 3–14 consecutive days) inhibits NLRP3 expression in microglia confirmed by reduced number of NLRP3+ IBA-1+ cells." (PMID 38659577, 2024). "In this study, we explored whether CX3CR1−/− mice can mediate the NLRP3 inflammasome‐induced microglial pyroptosis after ischemic stroke." (PMID 38421089, 2024). "Finally, we explored the involvement of the FPR1/NLRP3 axis in both LPS‐induced neuroinflammation and ischemic stroke models in mice." (PMID 39654367, 2024). "The NLRP3 inflammasome mainly influences the intracellular maturation of the precursors of IL‐1β/18, and its secretion into the extracellular environment triggers neuroinflammation after ischemic stroke." (PMID 38421089, 2024). "However, the role of activated-NLRP3 inflammasome in the process of IPC following ischemic stroke has not been fully understood." (PMID 37371374, 2023).
ischemic stroke (continued). "NLRP3 inflammasome could be regulated and activated by microglia receptors and molecules, along with chemoattractant and chemokines after ischemic stroke." (PMID 37915409, 2023). "This information provides a reference for scholars to further study NLRP3 in ischemic stroke." (PMID 37088947, 2023). "Furthermore, the anti-oxidative, anti-apoptotic, and neuroprotective regulation of curcumin in NLRP3 inflammasome, especially in ischemic stroke, is yet to be explored." (PMID 37915409, 2023). "Therefore, in ischemic stroke, investigations relating to cur–nanoparticles affecting NLRP3 inflammasome activation are warranted." (PMID 37915409, 2023). "We found that research of NLRP3 in ischemic stroke developed rapidly starting in 2011." (PMID 37088947, 2023). "Moreover, stress granules, DDX3X, and the NLRP3 inflammasome emerged as promising therapeutic targets for ischemic stroke treatment." (PMID 37580991, 2023). "NLRP3 inhibition by various interventions in ischemic stroke." (PMID 37915409, 2023). "Although various inhibitory mechanisms of Sirt1 on NLRP3 inflammasome have been discussed, whether Sirt1 exerts a protective effect on ischemic stroke by directly regulating NLRP3 deacetylation to inhibit pyroptosis remains unknown." (PMID 37622049, 2023). "Thus, targeting the NLRP3 inflammasome emerges as a plausible strategy for the development of anti-ischemic stroke medications." (PMID 37631097, 2023). "The data suggest that SGs, DDX3X, and NLRP3 inflammasome could potentially serve as therapeutic targets for the treatment of ischemic stroke." (PMID 37580991, 2023). "Moreover, it is well-established that the NLRP3 inflammasome plays a significant role in the progression of neurodegeneration during ischemic stroke." (PMID 37631097, 2023). "Notably, NLRP3 regulation of glial cell/macrophage polarization in ischemic stroke has been extensively studied in the following years and has become a major hotspot in this field." (PMID 37088947, 2023). "Multiple mechanisms regulate NLRP3 inflammatory vesicles after ischemic stroke." (PMID 37088947, 2023). "Therefore, it appears that neuro-thrombo-inflammation and the NLRP3 inflammasome are jointly implicated in the pathophysiological mechanism of CSVD and ischemic stroke or cerebrovascular disease in general." (PMID 36676165, 2023). "More importantly, autophagy mediators could regulate NLRP3 inflammasome activation following curcumin administration in the wake of ischemic stroke." (PMID 37915409, 2023). "The literature related to NLRP3 in ischemic stroke was published in 245 journals." (PMID 37088947, 2023). "NLRP3 inflammasome activation was reported to be a vital mediator of brain injury after ischemic stroke, which could trigger an inflammatory response, induce neuronal cell death, and aggravate brain injury." (PMID 37580991, 2023). "Actually, the HIF-1α/NLRP3 pathway has been recognized as a potential molecular target for treating ischemic stroke and traumatic brain injury because it regulates microglia activation and inflammatory cytokines release in the inflammatory cascade after brain injury." (PMID 36944982, 2023). "Nevertheless, the signaling mechanisms relating to how curcumin regulates NLRP3 inflammasome in inflammation and neural restoration following ischemic stroke are unknown." (PMID 37915409, 2023). "In the current study, we discovered that IPC could significantly inhibit the expression of NLRP3 inflammasome components and partially reduce the level of IL-1β and IL-18 at 6 h and 24 h following ischemic stroke, especially at the 24 h time point." (PMID 37371374, 2023). "Recently, research on the role of NLRP3 in ischemic stroke has developed rapidly worldwide." (PMID 37088947, 2023). "1B depicts the geographic distribution of NLRP3 and ischemic stroke research publications." (PMID 37088947, 2023). "Furthermore, previous studies have revealed time-dependent activation of the NLRP3 inflammasome pathway in ischemic stroke." (PMID 37620837, 2023).
ischemic stroke (continued). "Indeed, curcumin inhibits NLRP3 activation induced by ischemic stroke in animal models of transient middle cerebral artery occlusion/reperfusion (MCAO/R) via an upstream regulatory mechanism." (PMID 36677800, 2023). "Among these herbal medicines, the Scutellaria baicalensis extraction (SB) is known for its ability to inhibit NLRP3 inflammasome activation, reduce the generation of reactive oxygen species (ROSs), and mitigate neuronal apoptosis in the context of ischemic stroke." (PMID 37681864, 2023). "Additionally, miR-203a-3p has neuroprotective effects by inhibiting apoptosis, NLRP3 inflammasome activity, oxidative stress, and inflammation in hippocampal neurons in ischemic stroke models." (PMID 38095638, 2023). "In addition, the inhibition of the TLR3/NF-κB pathway by Renshen Shouwu extract increased the newly developed neurons, thus improving neurological deficit after ischemic stroke while NLRP3 inflammasome expression was downregulated." (PMID 37915409, 2023). "This study is the first bibliometric study on NLRP3 in ischemic stroke research worldwide." (PMID 37088947, 2023). "Based on these findings, future research should elucidate whether the stroke‐induced signaling through IL‐1β and NLRP3 inflammasome pathway could potentially trigger and exacerbate disturbances in the glucose metabolism in ischemic stroke patients." (PMID 35971650, 2022). "However, the relationship between PM2.5 and NLRP3 inflammasome activation during ischemic stroke has rarely been explored." (PMID 35403328, 2022). "Therefore, elucidating the mechanism of NLRP3 activation and intervening early after the onset of ischemic stroke are of great importance for the treatment and prognosis of ischemic stroke." (PMID 35600078, 2022). "In addition, treatment with PAP-1 intraperitoneally polarized microglia towards the M2 phenotype and inhibited NLRP3 inflammasome activation in ischemic stroke." (PMID 36499018, 2022). "It was demonstrated that ARC treatment could effectively suppress SIRT1-driven NLRP3 inflammasome activation by ischemic stroke in rat models." (PMID 36105479, 2022). "The NLRP3 inflammasome is a key upstream inflammatory response signal after ischemic stroke." (PMID 36013423, 2022). "Interestingly, blocking the NLRP3 inflammasome in pro‐inflammatory macrophages restored cardiac function and reversed the myocardial morphological changes observed in mice after ischemic stroke." (PMID 35971650, 2022). "Further studies would be required to investigate whether 4-EG directly inhibits NFκB and NLRP3 inflammasome activation to modulate brain injury in ischemic stroke." (PMID 35860274, 2022). "Indeed, 4-EG was previously reported to modulate NFκB and NLRP3 inflammasome activation, and the activation of NFκB and NLRP3 inflammasome was reported to induce brain injury in ischemic stroke." (PMID 35860274, 2022). "Although the pathogenesis of ischemic stroke remains unclear, many conventional medicines revealed the therapeutic effect on ischemic stroke function by inhibiting the activation of NLRP3 inflammasome." (PMID 35600078, 2022). "Therefore, there is enough evidence to suggest that targeting the molecular mechanisms pertaining to the role of NLRP3 inflammasome is a beneficial approach to help brain repair following ischemic stroke." (PMID 35328506, 2022). "Therefore, it is therapeutic in ischemic stroke to inhibit inflammatory response via inhibiting phenotype switch of microglia and NLRP3 inflammasome activation." (PMID 35600078, 2022). "For example, recent studies have documented how mir-223 may represent a new therapeutic expedient in case of ischemic stroke as it binds to a conserved site in the 3 UTR of the NLRP3, inactivates the latter, and inhibits the release of IL-1β." (PMID 36297283, 2022).
ischemic stroke (continued). "The infiltration of pro‐inflammatory macrophages into the heart and the activation of the NLRP3 inflammasome pathway have been proposed as key events that could lead to cardiac dysfunction after ischemic stroke in mice." (PMID 35971650, 2022). "Importantly, several studies have confirmed that SIRT1 plays a key role in neuroprotection by inhibiting the activation of NLRP3 inflammasomes after ischemic stroke." (PMID 36105479, 2022). "Some studies have proven that ROS can induce NLRP3 inflammasome activation after ischemic stroke." (PMID 35403328, 2022). "We therefore hypothesized that immunoproteasome/NF‐κB/NLRP3 signalling might be involved in the inflammatory mechanisms of ischaemic stroke." (PMID 34866334, 2022). "Therapeutic interventions that target activation of the immunoproteasome/NF‐κB/NLRP3 inflammasome pathway may provide novel prospects for the future treatment of ischaemic stroke." (PMID 34866334, 2022). "Within 24 h of the occurrence of ischemic stroke, the early activation of NLRP3 inflammasome in microglia and subsequent activation in neurons should be effectively targeted according to the cell type, thereby, reducing cerebral I/R injury, but the exact time needs further experimental studies." (PMID 35600078, 2022). "After the onset of ischemic stroke, the inhibition of NLRP3 inflammasome according to its expression time sequence could be considered as a future therapeutic target." (PMID 35600078, 2022). "However, besides our present findings and earlier studies, other results also suggest that neuronal NLRP3 can be involved in different pathologies, such as ischemic stroke, neurodegeneration, epilepsy, trauma and sterile inflammation." (PMID 35305649, 2022). "In the present study, we demonstrated that PM2.5 exposure triggered the activation of the NLRP3 inflammasome and pyroptosis under ischemic conditions, which may be mediated by increased ROS production after ischemic stroke." (PMID 35403328, 2022). "However, one animal study has shown that specific pyrophosphate inhibitors, such as Vx765, act as molecular blockers for NLRP3 inflammasome, thereby offering potential therapeutic value for ischemic stroke recovery and rehabilitation." (PMID 35328506, 2022). "In addition to the basic mechanism research, the results in clinical inspection of peripheral circulating plasma from patients who suffered from stroke also emphasized the significance of NLRP3 in the prognosis of ischemic stroke." (PMID 36204568, 2022). "Blocking or inhibiting the NLRP3 inflammasome may offer substantial promise to salvage neurological function during ischemic stroke." (PMID 35403328, 2022). "Moreover, it is proven that the impact of the unspecific medications (SFN, Genipin) on the inflammasomes besides NLRP3 is negligible in the treatment of ischemic stroke." (PMID 35600078, 2022). "In addition, recent studies have shown that inflammasome inhibitors have also been crucial treatment targets of microglial polarization in ischemic stroke, and NLRP3 inflammasomes have been proven to play a role in ischemic stroke." (PMID 36212660, 2022). "The NLRP3 inflammasome is involved in the inflammatory response of ischemic stroke." (PMID 36013423, 2022). "The in vivo middle cerebral artery occlusion (MCAO) animal model and the in vitro OGD stroke model are used to study the mechanism of ischemic stroke induction by activating the NF-κB pathway, NLRP3 inflammasome, and triggering a vicious cycle of oxidative stress, leading to neurotoxicity." (PMID 36232980, 2022). "Together, these findings suggest that therapeutic interventions that target the immunoproteasome/NF‐κB/NLRP3 inflammasome pathway may provide new opportunities for the future treatment of ischaemic stroke." (PMID 34866334, 2022). "Our previous report showed increased levels of IL‐1β and NLRP3 expression after ischaemic stroke, but NLRP3 deficiency or inhibition did not improve stroke outcome." (PMID 35137954, 2022).
ischemic stroke (continued). "Moreover, inhibition of either NLRP3 inflammasomes or the immunoproteasome attenuates both neuroinflammation and neurological deterioration during ischaemic stroke." (PMID 34866334, 2022). "Understanding the crosstalk of the NLRP3 inflammasome with other entities or mechanisms may be beneficial for the development of effective therapeutic strategies for ischemic stroke." (PMID 34059091, 2021). "As neuronal pyroptosis might be mediated by the activation of NLRP1 and NLRP3 inflammasomes in the course of ischemic stroke, western blot was performed to explore whether EE inhibited pyroptosis by suppressing the activities of NLRP1/NLRP3 inflammasomes." (PMID 34646128, 2021). "Thus, P2X7, P2Y12, and NLRP3 play essential roles in regulating the occurrence of neuroinflammation after ischemic stroke." (PMID 34276530, 2021). "In addition, possible targets and new strategies related to the NLRP3 inflammasome for the therapy of ischemic stroke are described." (PMID 34059091, 2021). "Similarly, our studies revealed that curcumin treatment ameliorated white matter injury after ischemic stroke by inhibiting microglia/macrophage pyroptosis through NF-κB suppression and NLRP3 inflammasome inhibition." (PMID 34630845, 2021). "However, it is interesting to note that the role of NLRP3 inflammasome in ischemic stroke is still controversial." (PMID 34559953, 2021). "Finally, several studies showed that pharmacologic or genetic deletion or inhibition of NLRP3 reduces infarct sizes and improves neurologic function after ischemic stroke." (PMID 32867797, 2020). "What is more, it was also reported that MCC950 improved neurological dysfunction at 24 h after cerebral I/R and promoted 28-day survival rate in diabetic mice with ischemic stroke, involving in the mRNA transcription level changes of NLRP3, caspase-1, and IL-1β." (PMID 32581721, 2020). "NLRP3 inflammasomes can regulate glial and neuronal cell death in ischemic stroke via enhancing generation and secretion of the pro-inflammatory cytokines including IL-1β and IL-18 and through pleiotropic impacts of cleaved-caspase-1 in regulating neuronal cell apoptosis." (PMID 32581721, 2020). "Besides, serum amyloid A can contribute to the NLRP3 inflammasome activation of microglial cells in ischemic stroke." (PMID 32581721, 2020). "It was clarified that that NLRP3 inflammasome is harmful in ischemic stroke again." (PMID 32153398, 2020). "This study suggests that caspase-12 and its potential regulation of NLRP3 inflammasome activation may be a promising target for treatment of ischemic stroke." (PMID 32788872, 2020). "Therefore, inhibition of NLRP3 inflammasomes via the AMPK pathway is neuroprotective in ischemic stroke." (PMID 31998437, 2020). "Our results indicate that caspase-12 and its potential regulation of NLRP3 inflammasome activation might be a promising target for treatment of ischemic stroke." (PMID 32788872, 2020). "In particular, the NOD-like receptor (NLR) family, pyrin domain-containing protein 3 (NLRP3) inflammasome, plays a critical role in many diseases involving sterile inflammation, especially ischemia-related diseases such as ischemic stroke, acute kidney injury, intestinal ischemia, and lung ischemia." (PMID 32867797, 2020). "Activation of the NLRP3 inflammasome can upregulate the expression of interleukin‐1β (IL‐1β) and then promotes the central nervous system cascade inflammatory response leading to the aggravation of nerve injury in ischemic stroke patients." (PMID 32529750, 2020). "H2S could play a neuroprotective role by inhibiting the activation of NLRP3 inflammasome in ischemic brain 66.The inhibitory effect of H2S on NLRP3 inflammasome has potential therapeutic value for ischemic stroke injury." (PMID 33110394, 2020). "Thus, NLRP3 inflammasome is an ideal therapeutic target due to its important role in the inflammatory response after ischemic stroke." (PMID 32581721, 2020).